MIR502 (microRNA 502)
Synonyms: hsa-mir-502; MIRN502; mir-502
Gene: MicroRNA gene on chromosome X (50,014,598 to 50,014,683, forward strand). Ensembl gene ENSG00000272080.
Gene Ontology:
Biological process: miRNA-mediated post-transcriptional gene silencing
Cellular component: RISC complex
Homologues: Orthologues: chimpanzee ptr-mir-502 (100% identical), macaque mml-mir-502 (91% identical), mouse Mir500 (91% identical), rat Mir500 (91% identical), guinea pig MIR502 (87% identical). Paralogues in human: MIR500A (88% identical), MIR501 (81% identical), MIR500B (78% identical).
Diseases named in the same sentence as MIR502 in open-access papers:
MIR502 is named in the same sentence as 2 diseases in open-access papers, as found by Europe PMC text mining. Sharing a sentence is not in itself a finding about the gene and the disease. The quoted sentences say what the papers report.
ovarian carcinoma (1 paper, 2020). A malignant neoplasm originating from the surface ovarian epithelium. "In our study, GLI2 as a downstream target of the Hippo signalling pathway was highly expressed due to the negative regulation by MIR502, resulting in an acceleration of the pathological process of ovarian cancer." (PMID 32660514, 2020). "We identified a set of biological functions and related signalling pathways that MIR502 might regulate in ovarian cancer." (PMID 32660514, 2020). "MIR502, which is regulated by NRF1, acts as a tumour suppressor gene to accelerate apoptosis and suppress proliferation by targeting the Hippo signalling pathway in ovarian cancer." (PMID 32660514, 2020).
MIR502 also shares sentences with these, for which no sentence is quoted: tumour (1 paper).